TNF (tumor necrosis factor)
Diseases named in the same sentence as TNF in open-access papers (continued):
Sharing a sentence is not in itself a finding about the gene and the disease.
osteoarthritis (continued). "Clinical studies confirmed that inflammatory cytokines such as TNF-α, IL-1β and IL-6 were highly expressed in osteoarthritis, which induced chondrocyte apoptosis and destroy articular cartilage." (PMID 34049522, 2021). "Inflammatory upregulation of 11β-HSD1 has previously been demonstrated when skeletal muscle samples from patients with osteoarthritis (OA) were stimulated with TNF-α ex vivo." (PMID 34360594, 2021). "In osteoarthritis and disc degeneration, TNF-α can activate the NF-κB and Erk pathways by binding specifically to TNF receptors, resulting in inflammatory changes and cartilage degeneration." (PMID 33936382, 2021). "In summary, our data reveal that Celecoxib ameliorated TNF-α-induced cellular senescence in human chondrocytes, exploring a novel mechanism whereby Celecoxib exerted its protective effects in osteoarthritis (OA)." (PMID 34895043, 2021). "Inflammation plays an important role in the pathogenesis of OA, in which the chondrocytes, synovial membrane, and surrounding tissues produce large amounts of inflammatory factors such as IL-1β, IL-6, TNF-α, that accelerate the progression of osteoarthritis." (PMID 34976968, 2021). "The beneficial results of PBA application under inflammatory conditions, such as in rat models of permanent ischemic stroke, osteoarthritis, or acute lung injury models, were shown to decrease the release of pro-inflammatory mediators IL-1β, TNFα, and IL-6." (PMID 34656124, 2021). "Main pro-inflammatory cytokines implicated in these processes are Interleukin-1 beta (IL1β) and Tumor Necrosis Factor alpha (TNFα), and their targeted inhibition has shown amelioration of osteoarthritis symptoms in diseased animal models." (PMID 34356815, 2021). "Several cytokines (such as IL-1β, lL-6, IL-8, IL-10, and TNF-α) and MMPs have been reported to be elevated in the joint space of patients with osteoarthritis." (PMID 34034772, 2021). "The initial findings were subsequently verified by a controlled double-blinded human trial in which monotherapy by LithoLexal® decreased the serum levels of TNF-α in individuals with moderate to severe osteoarthritis." (PMID 34940003, 2021). "To investigate the role of systemic inflammation and body composition in the development of IR, we compared RA patients, starting anti-TNF treatment, with matched osteoarthritis (OA) patients." (PMID 32776224, 2021). "Studies have proven that many pathological changes in osteoarthritis result from chronic low-grade inflammation mediated by inflammatory cytokines such as TNF-α and IL-1β." (PMID 34210342, 2021). "It is important to note that both TNF-α and IL-1β play an important role in the pathophysiology of osteoarthritis." (PMID 32947946, 2020). "Our data showed that FJHKO supplementation in rats with MIA induced osteoarthritis significantly decreased the expression of pro-inflammatory cytokines (IL-1β, TNF-α) and inflammatory factors compared with that in rats without FJH-KO supplementation." (PMID 33233504, 2020). "FLS isolated from RA (n = 5) and osteoarthritis (OA, n = 5) patients were stimulated with recombinant interleukin 17 (IL-17; 10 ng/ml) and tumor necrosis factor alpha (TNF-α; 10 ng/ml) for 1 h." (PMID 32414400, 2020). "The mRNA expression of pro-inflammatory mediators IL-1β and TNF-α decreased significantly in the FJH-KO supplemented rats compared with in rats with MIA induced osteoarthritis (p < 0.05)." (PMID 33233504, 2020). "The analysis of TNF-α concentrations in the SF can anticipate radiographic lesions in joints with osteoarthritis." (PMID 32365982, 2020). "In osteoarthritis, the cartilage degeneration is often a consequence of the action of inflammatory cytokines such as interleukin-1β (IL-1β) and tumor necrosis factor α (TNF-α)." (PMID 33121118, 2020). "In the pathogenesis of the degenerative joint disease, OA, inflammatory cytokines, such as IL-1, IL-6, and TNF-α, promote the synthesis of collagenase and MMPs resulting in the degradation of collagen type II." (PMID 33126603, 2020).
osteoarthritis (continued). "In these primary cultured chondrocytes, Hic-5 deficiency resulted in suppression of catabolic gene expression induced by osteoarthritis-related cytokines such as tumor necrosis factor α and interleukin 1β." (PMID 31673109, 2019). "In osteoarthritis, tumor necrosis factor-α (TNF-α) induced LRG-1 expression in the subchondral bone and articular cartilage, and LRG-1 contributed to angiogenesis-coupled de novo bone formation in the subchondral bone of osteoarthritis joints." (PMID 30760292, 2019). "In our study, genetic analysis also revealed the upregulated expression of IL-1, IL-6, and TNF-α in osteoarthritis cartilage in vivo was suppressed by SA." (PMID 30931327, 2019). "Our previous studies suggested that cytokines (e.g., IL-1β, IL-6, and TNF-α) expressed in articular chondrocytes during the pathogenesis of osteoarthritis and RA increase HIF-2α expression and protein accumulation under normoxia." (PMID 31098335, 2019). "The results showed that experimentally created osteoarthritis reduced the condylar cartilage thickness of rats and increased the gene expression of cytokines (IL-1β and TNFα) and positive cells of p65." (PMID 32083119, 2019). "Quantitative immunoexpression of IL-1 β, TNF and iNOS was more intense, P = 0.0194, 0.0293, 0.0124, respectively, in mouse knees from mice sacrificed 49 days after being subjected to an osteoarthritis (OA) model as compared to sham operated animals." (PMID 31860662, 2019). "Spontaneous secretion of some adipocytokines (MMP-3 and/or TNF, CCL2/MCP-1, IL-1Ra) was higher in osteoarthritis than rheumatoid ATs and probably caused by weaker anti-inflammatory treatment of OA patients." (PMID 30280295, 2019). "The levels of several inflammatory mediators, such as interleukin-1β (IL-1β) and tumor necrosis factor α (TNFα), are augmented in the joint tissue of osteoarthritis patients." (PMID 31905764, 2019). "Some studies showed that IL-1β and TNF-α contributed to the pathogenesis of osteoarthrosis and induced the inflammation and destruction of the joints." (PMID 32083119, 2019). "On the contrary, miR-23b was highly expressed in osteoarthritis-damaged cartilage; and miR-23b level in chondrocyte cells was increased under TNF-α treatment." (PMID 30314997, 2018). "Tumor necrosis factor alpha (TNF-α) is generally considered to be involved in the dysregulation of bone and cartilage remodeling in chondrodestructive diseases, especially osteoarthritis, in several in vitro and in vivo models." (PMID 30340603, 2018). "miR-145 attenuates TNF-α-driven cartilage matrix degradation in osteoarthritis by suppressing mitogen-activated protein kinase kinase 4 (MKK4) expression." (PMID 29844019, 2018). "Our goal was to quantify the dose-related effects of meloxicam treatment in the subchondral bone-involving, late phase of mono-iodoacetate-induced osteoarthritis, and to follow the levels of serum IL-6, IL-10 and TNFα, as markers of systemic inflammation." (PMID 28413731, 2017). "It has been demonstrated that inflammatory factors, including IL-6 and TNF-alpha, are involved in the pathophysiology of osteoarthritis." (PMID 28373981, 2017). "Cartilage dyshomeostasis contributes to osteoarthritis (OA) pathogenesis, and tumor necrosis factor (TNF)-α has critical role in this process by driving inflammatory cascades and cartilage degradation." (PMID 29072705, 2017). "Inflammatory cytokines, including IL-1β and TNF-α, downregulate mir-140 expression leading to the development of osteoarthritis, most likely due to accelerated inflammation and/or ADAMTS5 activation." (PMID 28099924, 2017). "Recent studies have suggested that the tumor necrosis factor-α (TNF-α) pathway is a potential target for the management of osteoarthritis (OA)." (PMID 28668088, 2017).
osteoarthritis (continued). "Equine BMSCs express high levels of galectin-1 mRNA relative to other articular cell types; however, BMSC galectin mRNA expression is diminished in the presence of pro-inflammatory cytokines prevalent in osteoarthritis (IL-1β and TNF-α)." (PMID 29096716, 2017). "Osteoarthritis of the hip joint results in an increase in pro-inflammatory mediators, specifically IL-6, IL-8 and TNF-α in the synovial fluid." (PMID 28468607, 2017). "NSAIDs commonly used for the treatment of osteoarthritis decrease IL-6, TNF-alpha and VEGF in the synovial fluid with an improvement in joint pain and function." (PMID 28468607, 2017). "The roles of recombinant IL-1β and TNF-α in osteoarthritis are well elucidated in in vitro and in vivo studies." (PMID 28036032, 2016). "Betalains have also been shown to express potent anti-inflammatory properties by reducing the pro-inflammatory cytokines tumor necrosis factor alpha (TNF-α) and interleukin-6 in patients with osteoarthritis." (PMID 29910288, 2016). "For example, in RA, fibroblast-like synoviocytes exhibit significantly higher levels of activated Syk than comparable cells from osteoarthritis patients or normal individuals and display reduced TNFα-dependent signaling following treatment with R406." (PMID 26756335, 2016). "These degrading enzymes are regulated inter alia by inflammatory mediators, like IL-1β and TNF-α, which are closely related to matrix breakdown and which also play a significant role in degenerative disease, like osteoarthritis." (PMID 25822615, 2015). "The aim of this work is to compare the expression profile of IL-15Ralpha, its ligand IL-15 and two validated cytokines targets in RA, TNF alpha and IL-6, in SF from RA regards to Osteoarthritis (OA) patients." (PMID 25879761, 2015). "It has been reported that TNFα and IL1β differently affect degenerative joint diseases such as osteoarthritis." (PMID 25157407, 2014). "It is known that pro-inflammatory cytokines, such as IL-1β and TNF-α, play a role in the pathogenesis of osteoarthritis; therefore, the present study established a model of OA using normal human articular cartilage cells stimulated by recombinant human IL-1β." (PMID 24348789, 2014). "Along this line of evidence, IL-17 was shown to enhance TNF-induced synthesis of IL-1, IL-6 and IL-8 by normal skin fibroblasts and osteoarthritis fibroblast-like synoviocytes." (PMID 24289089, 2013). "When administered by osmotic pump in the MIA osteoarthritis, MnL4 reduced pain, articular derangement, plasma TNF alpha levels, and protein carbonylation." (PMID 23861563, 2013). "Mid-zone distribution of CD163+ cells accompanied with increased expression of CD163 and TNF-α were further confirmed in the isolated Col-II+ chondrocytes from the knee cartilage of human patients with osteoarthritis, in contrast to the controls (both P<0.05)." (PMID 23326413, 2013). "The proinflammatory cytokine, TNF-α, is a critical mediator in osteoarthritis and rheumatic disease." (PMID 23861563, 2013). "In contrast, significantly increased numbers of CD163+ and TNF-α+ cells were observed in the superior mid-zone of knee cartilage from patients with osteoarthritis (OA) (P<0.05)." (PMID 23326413, 2013). "The production of IL-34 in FLS was up-regulated by TNFα in RA samples compared with osteoarthritis (OA) patients." (PMID 22264405, 2012). "Proinflammatory cytokines such as TNF-α and IL-1β have been shown to mediate cartilage degradation and apoptosis in chondrocytes in degenerative joint diseases such as RA and OA in humans as well as in animals." (PMID 19889203, 2009). "Pro-inflammatory cytokines, such as interleukin-1β (IL-1β) and tumor necrosis factor-α (TNF-α), play key roles in the pathogenesis of osteoarthritis (OA)." (PMID 18798984, 2008). "To investigate the mechanisms involved, we went on to use specific downregulation of IL-1 and/or TNF-α in these osteoarthritis cultures of synovial cells." (PMID 17177994, 2006).
osteoarthritis (continued). "In those with osteoarthritis, increased TNF-α levels in their synovial fluid might match the degree of their symptoms and the radiographic change of their disease." (PMID 40506990, 2025). "Moreover, a strong correlation was observed between synovial fluid and synovial tissue concentrations of IL-1β, IL-10, and TNF-α in degenerative joint disease." (PMID 40649748, 2025). "Furthermore, BM‐EV treatment has exhibited anti‐collagenase activity in the contexts of human osteoarthritic chondrocytes in vitro inflamed with TNF‐α and during in vivo collagenase‐induced murine osteoarthritis." (PMID 38587145, 2025). "GLP-1 RAs such as liraglutide, exenatide, lixisenatide, dulaglutide, and geniposide share common chondroprotective mechanisms in osteoarthritis, including suppression of NF-κB (reducing IL-6, TNF-α, and COX-2), inhibition of matrix-degrading enzymes (MMP-3/13, ADAMTS-4/5), and attenuation OS." (PMID 41158135, 2025). "Furthermore, i-PRF has demonstrated a significant reduction in the levels of pro-inflammatory cytokines, such as interleukin-1β and tumor necrosis factor-α, in experimental models of osteoarthritis." (PMID 40699638, 2025). "TNF-α is another pro-inflammatory cytokine connected to osteoarthritis." (PMID 40868398, 2025). "Moreover, gut microbiota metabolites can influence the function of local T and B cells in joints, modulating the production of inflammatory factors such as TNF–α and interleukin 6 (IL-6), which are key in the osteoarthritis pathological process." (PMID 40431441, 2025). "C3GC can also significantly reduce levels of MMP-3 and TNF-α in dogs with osteoarthritis." (PMID 40431555, 2025). "Co2+ stimulates the secretion of TNF-α and IL-6 from osteoarthritis fibroblasts." (PMID 41036386, 2025). "Pro-inflammatorycytokines (IL-1β, IL-6, and TNF-α) and anti-inflammatorycytokine (IL-2) levels in mouse models of osteoarthritis were evaluated,resulting in a reduction of serum expression of pro-inflammatory cytokinesand an enhancement of anti-inflammatory activity." (PMID 40300853, 2025). "Whereas the phagosome formation was enhanced, the osteoarthritis pathway was not substantially modified by the Notch2tm1.1Ecan mutation in the absence of TNFα." (PMID 40345585, 2025). "Additionally, the use of i-PRF showed a significant reduction in the levels of pro-inflammatory cytokines, such as IL-1β and TNF-α, in experimental models of osteoarthritis." (PMID 40699638, 2025). "In conclusion, our results support the clinical impact of smoking on OA development by showing the detrimental action of CSE on osteoarthritis-derived chondrocytes and the protective effects of TNF-alpha inhibitors, reinforcing the importance of this cytokine in the cartilage injury process." (PMID 40214444, 2025). "Tumor necrosis factor (TNF) plays a key role in degenerative joint disease." (PMID 41410796, 2025). "Furthermore, a PEMF can attenuate the progression of osteoarthritis in a murine model through the inhibition of TNF-α and IL-6 signals, which are crucial pro-inflammatory cytokines in the pathogenesis of osteoarthritis." (PMID 38731168, 2024). "Research has shown that golden buckwheat extract could delay the development of inflammation in rats with osteoarthritis of the knee by inhibiting the production of IL‐1β, TNFα, and IL‐6." (PMID 39139945, 2024). "However, in conditions like osteoarthritis, the synovial fluid also contains a diverse range of compounds implicated in inflammation and catabolism, such as IL6, IFNγ, MMPs, TNFα and IL-1β." (PMID 39126115, 2024). "These phenomena eventually lead to the deterioration of connective tissues and joints and, ultimately, to osteoarthritis, which results from the presence of various pro-inflammatory cytokines in OA chondrocytes, e.g., interleukin-1β (IL-1β), tumor necrosis factor-α (TNF-α), interleukin-6 (IL-6)." (PMID 39201248, 2024).
osteoarthritis (continued). "Thus, considering VD’s protective roles on the TNF-α treated human chondrocytes by regulating the proteoglycans turnover, VD is a potential nutrition and treatment strategies for osteoarthritis." (PMID 39275306, 2024). "Retinoic acid also prevents inflammation by inhibiting TNF-α and IL-1β in osteoarthritis models." (PMID 38527023, 2024). "In addition, both cell lines can produce the three main pro-inflammatory cytokines that are significantly elevated in osteoarthritis patients, namely, IL-1β, IL-6, and TNF-α." (PMID 39204123, 2024). "The in vitro equine osteoarthritis model developed in this work consists in explants of cartilage exposed to inflammatory cytokines, more precisely tumour necrosis factor (TNF)α and Interleukin (IL)-1β, as this was described as the best method to mimic OA-induced cartilage damage." (PMID 36271312, 2023). "Interleukin (IL)-1β, tumor necrosis factor (TNF)-α, and IL-6 seem to be the main proinflammatory cytokines involved in the pathophysiology of osteoarthritis, even though others, including IL-15, IL-18, IL-21, leukemia inhibitory factor (LIF), and chemokines are implicated." (PMID 36850304, 2023). "TNF-α could induce the production of various cytokines (matrix metalloproteinases (MMPs) and IL-34) to participate in the inflammatory response of osteoarthritis by activating different signals." (PMID 36681837, 2023). "Tumor necrosis factor (TNF), interleukin-6 (IL-6), and in particular interleukin-1 (IL-1) are the pro-inflammatory cytokines that can activate the production of inflammatory and catabolic factors, speeding up the progression of osteoarthritis." (PMID 37893118, 2023). "In osteoarthritis, TNF-α is regarded as the predominant pro-inflammatory cytokine." (PMID 37361231, 2023). "For example, proteolytic cleavage of SIRT1 induced by TNFα in osteoarthritis renders accumulation of a catalytically inactive 75 kDa resistant fragment that could be detected by immunohistochemistry." (PMID 37530744, 2023). "TNF-α, like IL-1β, is considered an essential inflammatory factor associated with the development of KOA, and plays a pivotal role in the degradation of cartilage matrix and bone destruction in osteoarthritis." (PMID 37718444, 2023). "In addition, a recent study found that PKR activation induced by TNF-α also plays an important role in the pathogenesis of osteoarthritis, triggering oxidative stress-mediated inflammation and MMP-13 in chondrocytes." (PMID 36838594, 2023). "Additionally, hsa_circ_0001658 expression was increased in dental pulp stem cells treated with TNF-α, which is a cell model of osteoarthritis." (PMID 37366063, 2023). "Taken together, LIPUS stimulation could realize articular cartilage regeneration based on hUC-MSC transplantation due to the inhibition of the TNF signaling pathway, which is of clinical value for the relief of osteoarthritis." (PMID 37069673, 2023). "We constructed an in vitro osteoarthritis model by adding TNF-α to the culture medium." (PMID 37361231, 2023). "Progressive structural changes in osteoarthritis (OA) involve synovial inflammation and angiogenesis, as well as activation of the proinflammatory cytokines tumor necrosis factor alpha (TNF-α) and interleukin (IL)-8, and the angiogenic factor vascular endothelial growth factor (VEGF)." (PMID 35256585, 2022). "Tumor necrosis factor-α (TNF-α) is a potential target for osteoarthritis (OA) treatment." (PMID 35720854, 2022). "IL-1β and TNF-α in patients with osteoarthritis can induce and obviously upregulate the expression of CRT in articular chondroblasts or synovial fibroblasts, CRTAC1 can be used as a biomarker to distinguish chondrocytes from osteoblasts and mesenchymal stem cells." (PMID 36507532, 2022). "TNF-α is one of the mediators secreted in early osteoarthritis." (PMID 35327152, 2022).